HLA-DPA2 (major histocompatibility complex, class II, DP alpha 2 (pseudogene))
Synonyms: formerly HLA-DP2A
Gene: Unprocessed pseudogene on chromosome 6 (33,091,753 to 33,097,295, reverse strand). Ensembl gene ENSG00000231461.
Diseases named in the same sentence as HLA-DPA2 in open-access papers:
HLA-DPA2 is named in the same sentence as 1 disease in open-access papers, as found by Europe PMC text mining. Sharing a sentence is not in itself a finding about the gene and the disease.
HLA-DPA2 shares sentences with these, for which no sentence is quoted: tumor (1 paper).